PIN1 (peptidylprolyl cis/trans isomerase, NIMA-interacting 1)
Diseases named in the same sentence as PIN1 in open-access papers (continued):
Sharing a sentence is not in itself a finding about the gene and the disease.
breast tumor (9 papers, 2007 to 2023). "We performed immunohistochemical staining of human breast tumor biopsy samples and scored for Pin1 and Rb phosphorylation (pS807/811)." (PMID 25675300, 2015). "In addition, PIN1 enhanced neoplastic cellular transformation and in vivo growth of breast tumors induced by IL-36γ." (PMID 35954317, 2022). "Furthermore, the role of PIN1 in IL-36γ-induced breast tumor growth was studied in a BALB/c mouse allograft model." (PMID 35954317, 2022). "In addition, a positive correlation between PIN1 and Rb phosphorylation has been shown in human glioma and breast tumor tissues." (PMID 30534074, 2018). "After standard data quality gene filtering methods were employed, 19 out of 21 genes were present (FBXW7 and PIN1 gave very low signal intensities) in the clustering analysis and clearly exhibited significant variation in expression across the 194 breast tumors." (PMID 17224074, 2007). "Additionally, PIN1 KO decreased IL-36γ-induced in vivo breast tumor growth to a certain extent." (PMID 35954317, 2022). "In a previous report, PIN1 was shown to bind to MEK and c-Jun, thus mediating the MAPK signaling pathway during breast tumor development." (PMID 35954317, 2022). "There is considerable evidence that PIN1 regulates the MAPK and STAT3 signaling pathways in breast tumor development through its interaction with MEK1, c-Jun and STAT3." (PMID 33800170, 2021). "The interaction of NONO with PIN1 increases the stability of NONO by inhibiting its proteasomal degradation, and this identifies PIN1 as a positive regulator of NONO in promoting breast tumor development." (PMID 37370134, 2023).
colon carcinoma (9 papers, 2011 to 2023). "It was found that Pin1 is overexpressed in many human cancers, including prostate, breast, lung and colon cancer, and the overexpression of Pin1 is associated with aggressive tumor progression and poor prognosis in cancer." (PMID 30934730, 2019). "Deadenylation assays using NEs from HCT116 and colon carcinoma RKO cells treated with juglone revealed that Pin1 inactivation inhibited nuclear deadenylation independently of stress conditions." (PMID 31749682, 2019). "A role for mammalian PIN1 in the control of HDAC family members has been unveiled in a study performed in human colon cancer cells treated with the HDAC inhibitor sulforaphane." (PMID 30873382, 2019). "For this purpose, endogenous PIN1 in human colon cancer (HCT116) cells was knocked down using PIN1 si-RNA, and stability of endogenous HIF-1α protein was monitored by a cycloheximide chase experiment." (PMID 26784107, 2016). "Here, we report that PIN1 directly interacts with hypoxia-inducible factor (HIF)-1α in human colon cancer (HCT116) cells." (PMID 26784107, 2016). "In present study, we observed a strong correlation between pin 1 expression and survival outcome, which inferenced pin1 expression as an excellent prognostic predictor for stage II A colon cancer." (PMID 27008710, 2016). "All these compounds exert their inhibitory effect on specific proteins, including RSK2, PI-3K, MEK1, Pin-1 and Fyn, which are highly expressed or overactivated in some cancers such as skin and colon cancer." (PMID 22693608, 2012). "Interestingly, PIN1 is overexpressed in many types of malignancies including breast, prostate, lung and colon cancers." (PMID 26784107, 2016). "Similarly, we previously showed that treatment with KPT6566 does not affect the level of Pin1 protein in Caco-2 colon cancer cells." (PMID 38020885, 2023).
lung carcinoma (9 papers, 2013 to 2022). "In conclusion, High expression levels of HDAC6 and Pin1 were found to be associated with poor outcome in lung cancer." (PMID 33162791, 2020). "Many tumors such as prostate and lung cancer in humans over-express Pin1, whereas its expression in AD patient’s brain is very low." (PMID 36199128, 2022). "Our data suggest that Pin1 acts as an important regulator to manage HDAC6 expression for cell motility in lung cancer cells." (PMID 33162791, 2020). "It is elusive that the higher expression levels of HDAC6 and Pin1 in the variety of lung cancer cell lines are coincident case or attribute to their biochemical or functional relevance." (PMID 33162791, 2020). "Intriguingly, higher expression levels of HDAC6 and Pin1 are coincidently present in a variety of lung cancer cells." (PMID 33162791, 2020). "In the present study, we attempted to elucidate the relationship between HDAC6 and Pin1 in lung cancer." (PMID 33162791, 2020). "To advance the functional and biochemical relationship of HDAC6 and Pin1 in lung cancer, we firstly quantified the expressions of HDAC6 and Pin1 in a variety of non-small lung cancer cell lines." (PMID 33162791, 2020). "Following, we attempt to understand what way the Pin1 sustain higher HDAC6 expression level in lung cancer cells." (PMID 33162791, 2020). "This is consistent with a previous study, in which the migration and invasion abilities of lung cancer cells were significantly reduced with the inhibition of PIN1 expression using PIN-1-specific siRNA." (PMID 24179535, 2013). "Interestingly, the change in Pin1 expression levels in lung cancer cells line is similar to HDAC6 expression patterns in those cells lines." (PMID 33162791, 2020). "Pin1 overexpression increased cell migration in lung cancer cells." (PMID 33162791, 2020). "The regulation of Pin1 on HDAC6 expression improves cell motility in lung cancer cells." (PMID 33162791, 2020). "In our previous study, we have been characterized that HDAC6 is one of Pin1 substrates and the involvement of Pin1 in HDAC6-mediated cell motility concerns with tumor metastasis in lung cancer cells." (PMID 33162791, 2020). "Thus, this study suggested that anti-Pin1 is promising strategies to downregulate HDAC6 expression and can be considered an anti-metastasis in lung cancers." (PMID 33162791, 2020). "In human lung cancer, cancer patients without Pin1 overexpression has longer cancer-related survival than cancer patients with Pin1 overexpression." (PMID 32258027, 2020). "Additionally, it has been suggested that Pin1 promotes drug resistance (chemotherapeutic agents, and tyrosine kinase inhibitors, TKIs) through an epithelial-mesenchymal transition (EMT) in lung cancer, breast cancer and cervical cancer, respectively 39-41." (PMID 33162791, 2020). "HeLa cervical, MDA-MB-231 breast and H1299 lung cancer cells were harvested in 1% NP40 lysis buffer and subjected to immunoprecipitation with anti-IgG or anti-Pin1 antibody, separately and blotted with anti-YAP/TAZ or Pin1 antibodies respectively." (PMID 31015482, 2019).
ovarian carcinoma (9 papers, 2007 to 2026). A malignant neoplasm originating from the surface ovarian epithelium. "We therefore knocked down PIN1 in BRCA2 null mammary epithelial cells and in a panel of BRCA1 and BRCA2 null ovarian cancer cells." (PMID 30590041, 2018). "PIN1 knockdown suppressed LYN Y397 phosphorylation in COV 362 cells (BRCA1 mutant ovarian carcinoma) and PEO-1 and PEO-4 cells (BRCA2 mutant ovarian carcinoma), but not in KURAMOCHI cells (BRCA2 mutant ovarian carcinoma)." (PMID 30590041, 2018).
dementia (8 papers, 2013 to 2024). Loss of intellectual abilities interfering with an individual's social and occupational functions. "How the Pin1-cis P-tau axis mediates the link between preE and dementia, diagnostic and therapeutic potentials of cis mAb, and avenues for future research are also discussed." (PMID 39857613, 2024). "We discuss evidence that enables us to speculate about the role of Pin1 as molecular link in the pathogenesis of type 3 diabetes i.e., the clinical association of dementia/AD and T2D." (PMID 30096758, 2018). "Therefore, Pin1 may be at the crossroad between AD and T2D-associated dementia, contributing to the clinical relationship of these two conditions in the T3D." (PMID 30096758, 2018). "Taken together, in brain neurons and placental trophoblasts, hypoxic stress/injury inactivates Pin-1, which induces cis P-tau aggregation that can spread between the cells and disrupt trophoblast–endothelial interactive functions, leading to dementia and preE features, respectively." (PMID 39857613, 2024). "We postulate that in severe preE that could lead to neurologic complications such as dementia, the Pin1-cis P-tau axis is disrupted, leading to increased cis P-tau aggregation in placental tissues and cistauosis." (PMID 39857613, 2024). "Pin1 enzyme plays a critical but opposite role in cancer and dementia." (PMID 32117730, 2020). "Because of these dual major roles on neuroprotection and metabolism, we and others speculate that impaired Pin1 function is one of the pivotal molecular links between neurodegeneration and impaired glucose metabolism, both manifesting in patients with dementia." (PMID 30096758, 2018). "Hence, relevance of Pin1 pathology to TBI may be taken into consideration in the future to assess its potential role in TBI-induced dementia and AD especially that many posttranslational modifications, which may follow protein synthesis, are similar between AD and TBI." (PMID 27920753, 2016).
glioblastoma (8 papers, 2013 to 2024). The most malignant astrocytic tumor (WHO grade IV). "PIN1-mediated mechanisms have also been implicated in the promotion of angiogenesis in glioblastoma." (PMID 30314361, 2018). "One of the first suggestions that PIN1 might contribute to gliomagenesis came from the demonstration that PIN1 binds to death-associated protein DAXX in glioblastoma cell lines." (PMID 30314361, 2018). "By downregulating DAXX via the ubiquitin-proteasome pathway, Pin1 has been found to inhibit DAXX-induced apoptosis in glioblastoma cells." (PMID 39624096, 2024). "We also performed the pull-down analysis with the wild-type and mutant Spastin constructs expressing T98G glioblastoma cells to confirm the involvement of Pin1 in the temporary alteration of Spastin’s localization in T98G cells." (PMID 36766769, 2023). "Real-time cell migration analysis was employed to investigate if the orientation of Spastin to actin filaments as a result of its interaction with Pin1 plays an active role in the migration and invasion abilities of T98G glioblastoma cells." (PMID 36766769, 2023). "In glioblastoma, loss of several factors, including PTEN, NF1 and KLF6, as well as increased activity/expression of others, including PIN1, MLK4 and microRNA-30e, have all been shown to contribute to NF-κB activation." (PMID 35922651, 2022). "Together, these findings provide evidence for roles of PIN1 in promoting the Warburg effect in glioblastoma cells, revealing an addition mode of PIN1 involvement in this deadly brain cancer." (PMID 30314361, 2018). "This review will focus on the involvement of PIN1, as well as other PPIases, in glioblastoma and medulloblastoma, the most frequent adult and pediatric primary brain tumors, respectively." (PMID 30314361, 2018). "A case in point is offered by the suggestion that abnormal PIN1 activation enhances glioblastoma cell survival through inhibition of apoptotic pathways." (PMID 30314361, 2018). "PIN1 promotes the activity of other factors with the potential to promote angiogenesis in glioblastoma, in addition to VEGF." (PMID 30314361, 2018). "It will be necessary to increase our understanding of the downstream targets of PIN1 during specific oncogenic mechanisms, and in distinct glioblastoma cell populations, to be able to further elucidate the contribution of PIN1 to gliomagenesis." (PMID 30314361, 2018). "PIN1 impairment was proposed to affect the angiogenic potential of glioblastoma cell lines based on chick chorioallantoic membrane assays." (PMID 30314361, 2018). "This review will discuss studies providing evidence for multiple roles of PIN1 and other PPIases in glioblastoma and medulloblastoma, the most frequent adult and pediatric primary brain tumors." (PMID 30314361, 2018). "These combined results provide evidence suggesting that PIN1 overexpression is correlated with mechanisms promoting angiogenesis in glioblastoma including, but not limited to, the promotion of NF-κB, VEGF, and IL-8 activation." (PMID 30314361, 2018). "These cell culture systems can hardly recapitulate the in vivo heterogeneity of glioblastoma, making it virtually impossible to discern in which specific glioblastoma cell subpopulations PIN1 exerts its main functions." (PMID 30314361, 2018). "It was through the combined use of PIN1-directed RNAi reagents and juglone-mediated pharmacological inhibition that PIN1 impairment was shown to also impact the migratory potential of glioblastoma cells, resulting in decreased cell migration in vitro." (PMID 30314361, 2018). "This function is relevant in the context of glioblastoma because PIN1 can enhance NF-κB activity in glioblastoma cells." (PMID 30314361, 2018). "Here, we identified Pin1 as a novel interaction partner of Spastin and showed that this interaction is required for transient co-localization of Spastin with actin filaments to enhance migration and invasion of T98G glioblastoma cells." (PMID 36766769, 2023).
glioblastoma (continued). "Furthermore, we discovered that endogenous Spastin is directed to actins in T98G glioblastoma cells upon Pin1 overexpression, which is comparable to EGF treatment." (PMID 36766769, 2023). "In conclusion, our findings demonstrated that M87-Spastin has a role in the T98G glioblastoma cell migration and invasion processes, and this involvement is controlled by its shift from microtubules to actin filaments via its interaction with Pin1 through its MBD." (PMID 36766769, 2023). "Given this, developing a bio-mimetic medication that may interfere and disrupt Spastin’s MBD interaction with Pin1 may be a critical step toward treating and preventing the recurrence of glioblastoma tumors." (PMID 36766769, 2023). "All these findings indicate that M87-Spastin could contribute to the migration and invasion ability of T98G glioblastoma cells only if it is directed to actin filaments after interacting with Pin1 owing to its phosphorylation in the MBD region." (PMID 36766769, 2023). "Since our real-time cell analyses clearly show that the interaction between Spastin and Pin1 promotes the migration and invasion capacities, this interaction might be a therapeutic target for glioblastoma treatment." (PMID 36766769, 2023). "Since Pin1 is known to alter the subcellular localization of its target proteins, in this study, we investigated whether Pin1 plays a role in the transient localization change in Spastin in migrating T98G glioblastoma cells." (PMID 36766769, 2023). "Most previous studies of PIN1 involvement in glioblastoma suffer from a common limitation, namely the fact that they were mainly based on in vitro investigations using established glioblastoma cell lines." (PMID 30314361, 2018). "Taken together, these findings show that several PPIases, in addition to PIN1, participate in the regulation of glioblastoma growth, survival, angiogenesis, and metabolism, thus providing further evidence for multiple functions of these enzymes in gliomagenesis." (PMID 30314361, 2018). "It remains to be determined whether PIN1 mediates a pro-survival effect in the proliferating or the resting glioblastoma cell pool (or both) in vivo." (PMID 30314361, 2018). "Moreover, because this interaction is unlikely to occur in healthy glial cells due to the low expression of Spastin and Pin1, targeting this interaction may only influence cancer cells; hence, targeting this interaction may be a safe alternative for improving glioblastoma therapy." (PMID 36766769, 2023). "Our findings imply that identifying kinases that phosphorylate Pin1 recognition motifs in MBD, will aid in the development of therapeutic drugs that may be beneficial in the treatment of cancer types with high invasion capacity such as glioblastoma." (PMID 36766769, 2023). "Furthermore, in glioma stem cells (GSC), Pin1 undergoes deubiquitination and stabilization via the action of USP34, which is instrumental in facilitating glioblastoma (GBM) initiation, progression, and therapeutic resistance." (PMID 39624096, 2024). "However, Pin1 expression does not appear to significantly correlate with FOXM1, CENPF and Cyclin B1 expression in at least mammary, ovarian, renal and endometrial carcinomas and glioblastoma, suggesting the regulation of FOXM1 activity by Pin1 might be restricted to subsets of cancers." (PMID 26279295, 2016).